CDH1 (cadherin 1)
Diseases named in the same sentence as CDH1 in open-access papers (continued):
Sharing a sentence is not in itself a finding about the gene and the disease.
breast carcinoma (continued). "GRHL2 levels correlated positively with CDH1 (E-cadherin) levels and negatively with ZEB1 in the CCLE dataset and TCGA datasets from breast cancer, ovarian cancer and colorectal cancer." (PMID 32676163, 2020). "Note that CDH1 and PVRL2 appear in all clusters at the same time, which probably means that they play a very important role in the immune evasion of breast cancer." (PMID 33304391, 2020). "We were able to validate multiple correlations with DEK expression and both down- and up-regulated genes in primary human breast cancers, including CCL5, CDC45, CDH1, and HDAC7." (PMID 32708944, 2020). "Other gene knockouts (RUNX1, CDH1, and ARID1B) have similar effect, consistent with their reported tumor-suppressor roles in breast cancer or other cancer types." (PMID 31980032, 2020). "EMAT clusters displayed distinct expression profiles for CDH1, VIM, RHOA, and JUP, well-accepted biomarkers of epithelial (E), mesenchymal (M), amoeboid (A), and collective cell migration in breast cancer, respectively." (PMID 32641077, 2020). "Taken together, these results indicate that SPDEF/CDH1 signaling is required for the GRIK3‐mediated cell proliferation, migration, and invasion of breast cancer cells." (PMID 30977227, 2019). "Data was obtained from database GSE9586 and demonstrated that CDH11 mRNA level was prominently elevated in the metastatic breast cancer cells along with vimentin, CTNNB1 (β-catenin) as compared to E-cad (CDH1)." (PMID 31248373, 2019). "Expression of miR-23b/27b/24 cluster promotes breast cancer lung metastasis by targeting metastasis-suppressive gene prosaposin; these miRNAs also promote TGF-β1-induced EMT by directly targeting CDH1 and activating Wnt/β-catenin signaling." (PMID 31130637, 2019). "Further reported CASC9 target genes were CDK4, CyclinD1 (CCND1), E-Cadherin (CDH1) and BCL2 in lung adenocarcinoma, ESCC cells, oral squamous cell carcinoma and in breast cancer." (PMID 31412811, 2019). "Basal-like breast cancer cells that express mesenchymal characteristics overexpress EZH2, co-ordinates with SUZ12 to form PRC2 complex and recruited to CDH1 promoter to represses E-cadherin." (PMID 35582717, 2019). "In order to determine the variation, we have compared the level of general breast cancer markers (MGB1, HER2) and genes used for CTCs-EBF classification into EMT phenotypes (CK19, CDH1, VIM, CDH2, PLS3)." (PMID 30634453, 2019). "Further inoculation of control and Cdh1-depleted MDA-MB-231 and BT474 cells into immunodeficient mice revealed that compared to control cells, Cdh1-depleted breast cancer cells developed larger tumors in vivo." (PMID 31420536, 2019). "Knocking-down ZEB2 (ZEB2-KD) in the mesenchymal-like MDA-MB-231 breast cancer cell line (which expresses more endogenous ZEB2 and less RAB25 than MCF7 cells) induced the expression of RAB25 and CDH1." (PMID 30445998, 2018). "In breast cancer, Snail recruits LSD1 to epithelial gene promoters including that of CDH1, where LSD1 mediates H3K4me2 demethylation and consequent transcriptional silencing." (PMID 29311580, 2018). "It has been reported that knockdown of TRIM29 in breast cancer cells was sufficient to induce EMT with increased level of CDH2 and VIM and decreased level of CDH1 via suppression of TWIST." (PMID 29228692, 2017).
breast carcinoma (continued). "Since CDH1 is critical for stem cell maintenance and regulation of epithelial cells, it raises a question whether other CDHs are involved in the maintenance of CSCs in breast cancer in addition to CDH1, especially under circumstances when CDH1 is deleted or lost, which remains relatively unexplored." (PMID 28392805, 2017). "Construct containing the CDH1 ORF and siRNA were respectively used to increase or decrease E-cadherin expression in breast cancer cells." (PMID 29050223, 2017). "Phenformin also dose-dependently upregulated mRNA levels of CDH1 with concomitant downregulation of VIM, SNAI1, and SNAI2, indicating that phenformin hinders EMT at the transcriptional level in breast cancer cells." (PMID 28947975, 2017). "In breast cancer cell lines, authors showed that the expression of CD151, VIM, and SNAI2 were suppressed, while CDH1 (an epithelial marker) was upregulated by miR-506." (PMID 28405738, 2017). "This is in support with the previous findings have suggested that, CDH1 and GSTP1 promoter regions tend to be methylated in breast cancer cells." (PMID 28979331, 2017). "The mean transcript expression of CDH1 and KRT18 were lower in the basal B breast cancer cells with low FRK transcript levels as compared to Basal A and Luminal cells that harbor high FRK transcript levels (P<0.05)." (PMID 29348886, 2017). "Although ZEB1/CDH1 are repressed by miR-200b, restoration of ZEB1 expression in breast cancer cells expressing miR-200b was unable to modify their metastatic potential, suggesting additional mechanisms underlying metastasis." (PMID 27081085, 2016). "To characterize the expression of AXL in vitro, we analyzed the expression of the tyrosine kinase, EMT (CDH1 and VIM), and basal (EGFR, KRT5, and KRT6A) markers in 15 breast cancer cell lines by quantitative real-time PCR (qRT-PCR)." (PMID 28721387, 2016). "Epithelial–mesenchymal transition (EMT) is a central event during cancer metastasis, a process that has been shown to be regulated, in human breast cancer MCF-7 cells, by ZIP6 down-regulation of E-cadherin (CDH1)." (PMID 27274087, 2016). "With mutational or epigenetic inactivation of the cell adhesion molecule E-cadherin (CDH1) being confined almost exclusively to ILC, this tumor entity stands out from all other types of breast cancers." (PMID 25757734, 2015). "The involvement of SPARC, a small calcium-binding glycoprotein that modifies cell-matrix adhesion, was already shown in breast cancer and melanoma progression due to its ability to induce MMP2 and SNAI1 and repress CDH1, hereby promoting ECM invasion and EMT." (PMID 24429391, 2014). "Claudin-low tumors express decreased levels of CDH1, are enriched for EMT markers, and are CD24 low/CD44 high, which are features of self-renewing breast cancer stem cells." (PMID 25252859, 2014).
breast carcinoma (continued). "The expression profile of miR-655 was compared with that of each of seven typical EMT-related genes (CDH1/E-cadherin, miR-141, -200a, -200b, -200c, -205, and VIM) in a panel of 23 pancreatic cancer cell lines and a breast cancer cell line, MDA-MB-231." (PMID 23690952, 2013). "The claudin-low subtype is a recently identified molecular subtype of human breast cancer characterized by low expression of tight junction and adherens genes including CLDN3, CLDN4, CLDN7 and CDH1." (PMID 24009024, 2013). "miR-9 directly targets CDH1, which is the E-cadherin coding gene, leading to increased cell motility and invasiveness of SUM149 human breast cancer cells." (PMID 22200848, 2012). "In breast cancer, multiple TSG are hypermethylated and downregulated, including for examples BRCA1, RASSF1A, p16, FHIT, and CDH1." (PMID 22110708, 2011). "Reduction of CDH1 is often accompanied by reciprocally increased expression of CDH2, and indeed CDH2 has been shown to promote breast cancer cell invasiveness in various studies." (PMID 19636430, 2009). "Recently, CDH1 has been reported to be downregulated by an epithelial–mesenchymal transition (EMT) regulator, TWIST, which plays an essential role in breast cancer metastasis, especially of the diffuse type." (PMID 19107131, 2009). "Public data analysis from breast cancer patients revealed post-radiotherapy upregulation of the β-catenin pathway, with elevated CTNNB1, MYC, and CD44 expression, alongside reduced CDKN2A and CDH1 levels, supporting clinical relevance." (PMID 40657369, 2025). "We previously reported that TWIST1 induces the transcriptional activation of mesenchymal genes such as VIM (Vimentin) and SNAI2 (Snail 2) but induces the transcriptional repression of epithelial genes such as CDH1 (E-cadherin) and ESR1 (ERα) in breast cancer cells." (PMID 38893094, 2024). "In breast cancers, homotypic CTC clusters demonstrate remarkable resilience against anoikis by preserving cell–cell contacts through a variety of complexes, including plakoglobin (JUP), homophilic CD44 interactions, E-cadherin (CDH1) and nectin-4." (PMID 38506114, 2024). "When CDH1 mutations were present, 91% of breast carcinomas lacked E-cadherin expression, and the remaining 9% with CDH1 mutations maintained E-cadherin expression, all involving missense mutations." (PMID 39594781, 2024). "Additional genes tested with a definite link to breast cancer included CDH1 (n=29) and BARD1 (n=19) testing negative in addition to 72 samples testing negative for BRIP1." (PMID 38609177, 2024). "CDH1 suppression induces EMT and subsequently triggers breast cancer metastasis." (PMID 38200154, 2024). "Further analysis demonstrated that the CDH1 mRNA levels were not significantly changed across the major cancer stages in breast carcinoma, colon carcinoma, pancreatic carcinoma, lung carcinoma, and endometrial carcinoma." (PMID 37189027, 2023).
breast carcinoma (continued). "CTNNA1 expression significantly decreases in basal-like breast cancer with negative CDH1, which shows a negative correlation with the level of TNF-β and Re1B." (PMID 36741258, 2023). "In breast cancer, overexpression of the KHKA isoform induced metastasis through 14-3-3 phosphorylation and recruitment of SLUG to the Cadherin 1 (CDH1) promoter under fructose-fed conditions, suggesting that KHKA, rather than KHKC, is necessary and sufficient for fructose-induced cell invasion." (PMID 37559908, 2023). "The relative staining intensities of CDH1 were negative (two cases), moderate (one case), and strong (eight cases) in breast cancer samples." (PMID 36315446, 2022). "In breast cancer, the APC, CDH1, and CTNNB1 genes are highly methylated." (PMID 35743249, 2022). "The aim of this review is not to compile each and every paper ever published on CDH1 gene methylation in human breast cancer." (PMID 36139537, 2022). "For example, TBL1X promotes EMT of breast cancer cells by acting as a cofactor of ZEB1 to regulate the expression of CDH1, and the high expression of TBL1X contributes to metastasis of breast cancer and is correlated with the poor prognosis of patients with breast cancer." (PMID 35173544, 2022). "In addition to SALL4 and SALL2, studies in breast cancer lines showed that SALL1 inhibition increases cell migration and correlates with decreased cadherin 1 expression." (PMID 36438565, 2022). "mRNA levels of CDH1/11/13 were relatively high in breast cancer patients classified as stage IV with metastasis but without statistical significance." (PMID 36315446, 2022). "Cadherin 1 (CDH1), CDKN2A, the runt‐related transcription factor 3 (RUNX3), BRCA1 and RASSF1A are reported to be suppressed by DNMT3B‐dependent DNA hypermethylation in gastric or breast cancers." (PMID 34133843, 2022). "Another study demonstrated that G9a, a histone methyltransferase responsible for histone H3 lysine 9 (H3K9) mono- and demethylation, is required for EMT-induced DNA methylation at the E-cadherin (CDH1) promoter in three model cell lines, and in Claudin-low breast cancer CLBC." (PMID 36076918, 2022). "The lack of changes in mesenchymal marker expression upon activation of C/EBPδ or CDH1 suggests that C/EBPδ-induced CDH1 merely induces a partial Mesenchymal-to-Epithelial Transition (MET) in these cells, a phenomenon that has similarly been described in breast cancer." (PMID 36359732, 2022). "The expression of key markers associated with proliferation (MKI67, PCNA, CCNB1, MYBL2, BUB1, CCND1), apoptosis (BCL2, CASP7, CASP8, CASP9, CASP3, BAX, APAF1), differentiation (CDH1, CD24, EPCAM, ESR1, NGFR, RUNX1), and breast cancer stemness (CD44, ITGA6, DNER, ALDH1A3, ABCG2, PROCR) was assessed." (PMID 35183258, 2022). "CDH1, CDH2, and CDH12 exhibited strong intensities in cell nuclei in breast cancer samples." (PMID 36315446, 2022). "Similarly, genetic and epigenetic alterations in E-Cadherin (CDH1) relates to aberrant expression and microsatellite instabilities in breast cancer patients have also been related to the incidence of breast cancer." (PMID 33761889, 2021). "In this study, CDH1 c.1003 C > T was reported in a breast cancer patient without familial history for DGC." (PMID 33827469, 2021).
breast carcinoma (continued). "Additional larger case-control studies or segregation analysis in families might be needed to fully elucidate the breast cancer risks for PTEN, CDH1, and STK11 in Chinese women." (PMID 34606182, 2021). "In particular, heterotypic adherens junctions between breast cancer cell-derived CDH1 and CDH2 in an osteogenic niche can support bone colonization of circulating breast cancer cells and stimulate the mechanistic target of rapamycin (mTOR) pathway-driven micrometastasis formation." (PMID 34831167, 2021). "Among the individuals with pathogenic variants, 50% were diagnosed with breast cancer and had mutations in BRCA1, CDH1 and MUTYH – gene not typically associated with this cancer." (PMID 33827469, 2021). "The two cases affected by breast cancer were not tested for CDH1 alterations and their histological subtype is currently not known." (PMID 34503169, 2021). "Poorly differentiated adenocarcinoma cells that retained expression of E-cadherin (CDH1), as well as CDH1-negative spindle-like cells within mammary tumors of MMTV-Flp FSF-KrasG12D Rosa26CAG-FSF-GFP triple transgenic females, were GFP-positive." (PMID 34675248, 2021). "The gene expression profiling from microarray analysis showed that the expression levels of E-Cadherin/CDH1, a critical gene in maintaining cell–cell adhesion and epithelial–mesenchymal transition, were significantly upregulated in breast cancer cells when ATAD3A was knocked down." (PMID 33113782, 2020). "It was observed that 40.9% of breast cancers and 61.5% of lung metastasis samples were hypermethylated in the CDH1 promoter, while none of the normal breast samples displayed CDH1 methylation." (PMID 32301282, 2020). "In support of the dissociation of Slug from the EMT processes, expression of Slug protein or E-cadherin (CDH1) mRNA were not correlated with the activation of a core EMT gene expression signature in breast cancer." (PMID 32760736, 2020). "Having identified Src as an upstream kinase to displace Cdh1 from the APC core complex, we next sought to explore if inhibition of Src could restore the E3 ligase activity of APCCdh1 in breast cancer cells." (PMID 31420536, 2019). "Expression of VIM, CDH1, CDH2, PLS3, CXCR4, CD44 and NANOG have been found in healthy controls and the maximal expression levels of these genes were the threshold beyond which CTCs-EBF of breast cancer patients were considered positive." (PMID 30634453, 2019). "Our results underpin the existence of an APC-free, cytoplasmic population of Cdh1 in breast cancer cells whose function has not been fully explored." (PMID 31420536, 2019). "In addition, blockage of E-cadherin and a down-regulation of CDH1 leads to enhanced spheroid formation of MCF-7 breast cancer cells." (PMID 31261642, 2019). "For example, in breast cancer, miR-9 promotes EMT by targeting cadherin 1 (CDH1)." (PMID 31244281, 2019). "That is, CDH1 and STK11 have a limited contribution to breast cancer in unselected Japanese women." (PMID 30287823, 2018). "Previous investigations had reported that TSC2, ARID1A, AXIN1, CASP8, CDH1, and ASXL1 could play roles in tumor suppression in diverse cancer types, including breast cancer." (PMID 29414922, 2018).